S1PR1-DT (S1PR1 divergent transcript)
Synonyms: LISPR1
Gene: Long non-coding RNA gene on chromosome 1 (101,228,769 to 101,236,815, reverse strand). Ensembl gene ENSG00000225938.
Diseases named in the same sentence as S1PR1-DT in open-access papers:
S1PR1-DT is named in the same sentence as 1 disease in open-access papers, as found by Europe PMC text mining. Sharing a sentence is not in itself a finding about the gene and the disease.
S1PR1-DT shares sentences with these, for which no sentence is quoted: multiple sclerosis (1 paper).